GSDMD (gasdermin D)
Diseases named in the same sentence as GSDMD in open-access papers (continued):
Sharing a sentence is not in itself a finding about the gene and the disease.
periodontitis (19 papers, 2021 to 2026). An acute or chronic inflammatory process that affects the tissues that surround and support the teeth. "We detected upregulated expression and enhanced cleavage of GSDMD in PBMCs from patients with periodontitis, which was positively associated with the severity of periodontitis in patients." (PMID 37506160, 2023). "We reported that elevated mRNA and protein levels of IL‐1β and GSDMD, decreased levels of Synoviolin mRNA and protein, and decreased ubiquitination of GSDMD were associated with periodontitis." (PMID 37506160, 2023). "CASP4/GSDMD initiated by bacterial LPS is shown to cause pyroptosis of periodontal ligament stem cells in periodontitis." (PMID 35844512, 2022). "Taken together, these results indicated that restoring the level of BMAL1 alleviates circadian disruption-aggravated periodontitis via lessening GSDMD-mediated pyroptosis." (PMID 40000642, 2025). "GSDMD, a key executor that triggers pyroptosis, serves as an attractive checkpoint in host defences against inflammatory and autoimmune diseases, such as periodontitis." (PMID 39626954, 2025). "Overall, synoviolin suppressed inflammasome activation and periodontitis by promoting GSDMD ubiquitination, suggesting its potential as a therapeutic target for managing periodontitis." (PMID 39626954, 2025). "GSDMD-mediated pyroptosis accelerated periodontitis progression, whereas downregulated BMAL1 under circadian disruption further aggravated periodontal destruction by increasing GSDMD activity." (PMID 40000642, 2025). "And restoring the level of BMAL1 by circadian recovery and SR8278 injection alleviated simulated shift work-exacerbated periodontitis via lessening GSDMD-mediated pyroptosis." (PMID 40000642, 2025). "CASP4/GSDMD triggered by bacterial LPS leads to focal death of periodontal ligament stem cells in periodontitis patients." (PMID 38800469, 2024). "Histological analyses of mouse periodontitis models confirmed the expression of NLRP3 as well as GSDMD was downregulated in CKO mice." (PMID 38696610, 2024). "The analysis of ROC curves revealed that GSDMD levels can be used to accurately differentiate between healthy individuals, patients with severe periodontitis, and patients with ASCHD." (PMID 39071510, 2024). "The co‐staining results of immunofluorescence showed that caspase‐1 and GSDMD were enriched in macrophages in patients with periodontitis." (PMID 38803043, 2024). "Correspondingly, we detected obviously increased protein amounts of cleaved GSDMD (p31) and caspase‐1 (p20) in PBMCs isolated from patients with mild and severe periodontitis." (PMID 37506160, 2023). "We confirmed the interaction between Synoviolin and GSDMD by immunoprecipitation in vitro and found that the expression of Synoviolin was decreased in PBMCs isolated from patients with periodontitis, which was correlated to decreased ubiquitination of GSDMD." (PMID 37506160, 2023). "In contrast, the ubiquitination of GSDMD was obviously decreased in PBMCs from patients with periodontitis, which indicated the suppression of GSDMD ubiquitination in these PBMCs." (PMID 37506160, 2023). "PDLSCs can undergo gasdermin-D (GSDMD)-dependent pyroptosis, leading to periodontitis by increasing IL-1β release, enhancing inflammation, and promoting osteoclastogenesis." (PMID 36973490, 2023). "The expression of IL‐1β, GSDMD, and Synoviolin in peripheral blood mononuclear cells from patients with periodontitis was determined." (PMID 37506160, 2023). "By establishing a model of experimental diabetes mellitus–periodontitis in rats, we found that IL-1β and gasdermin D were highly expressed, leading to aggravated destruction of periodontal tissue." (PMID 37047282, 2023). "In the present study, we found that there was upregulated mRNA expression of IL‐1β and GSDMD in PBMCs, as well as an increased serum level of IL‐1β in patients with periodontitis, suggesting the activation of inflammasome in periodontitis." (PMID 37506160, 2023).
periodontitis (continued). "In PBMCs isolated from patients with mild and severe periodontitis, the ubiquitination of GSDMD was obviously decreased compared to PBMCs isolated from healthy donors." (PMID 37506160, 2023). "In the present study, we found that Synoviolin was downregulated in PBMCs from patients with periodontitis, which was correlated to decreased ubiquitination of GSDMD, elevated GSDMD protein level, and increased inflammasome activation in these PBMCs." (PMID 37506160, 2023). "Here, we evaluated the effects of the E3 ligase Synoviolin on GSDMD expression and on periodontitis." (PMID 37506160, 2023). "CASP8, which can cleave GSDMD, resulting in pyroptosis activation, has been shown to be expressed at lower levels in aggressive periodontitis as compared to chronic periodontitis." (PMID 35844512, 2022). "In the context of periodontitis, a number of recent in vitro and animal experimental studies have also documented the activation of GSDMD and NLRP3 inflammasome pathways, including that by P. gingivalis lipopolysaccharide (LPS) stimulation." (PMID 35844512, 2022). "Studies restricted their focus on caspase-1/GSDMD, the role of caspases, GSDMs, granzymes, and ELANE, which, beyond caspase-1/GSDMD, remain to be fully elucidated in periodontitis." (PMID 36093182, 2022). "As elevated levels of LPS from gram-negative bacterial and inflammatory caspases were often detected in patients with periodontitis and in murine periodontitis, this provided a prerequisite for the activation of GSDMD and IL-1β release." (PMID 33869229, 2021). "Collectively, these results indicate that GSDMD-driven pyroptosis is an indispensable mechanism involved in the pathogenesis of periodontitis." (PMID 33869229, 2021). "We next detected the expression of GSDMD (the key executor of pyroptosis) in periodontal tissues from periodontitis patients." (PMID 33869229, 2021). "Here, we found that PDLSCs suffered GSDMD-dependent pyroptosis to release interleukin-1β (IL-1β) during human periodontitis." (PMID 33869229, 2021). "In this study, combining human periodontitis specimens (n = 87), we found that PDLSCs underwent GSDMD-mediated pyroptosis with typical cell swelling and IL-1β release during periodontitis." (PMID 33869229, 2021). "Overall, our data demonstrated that GSDMD-dominant PDLSC pyroptosis played a pivotal role in the pathological damage of periodontitis." (PMID 33869229, 2021). "To further prove PDLSC was the cell type that pyroptosis happened in periodontitis, we also examined the localization pattern of GSDMD." (PMID 33869229, 2021). "To verify this hypothesis, we first clarified the role of GSDMD-mediated pyroptosis acted in periodontitis progression." (PMID 40000642, 2025). "Furthermore, restoring normal circadian rhythm and using SR8278 activates the expressions of BMAL1 and inhibits GSDMD-mediated pyroptosis, thereby ameliorating circadian disruption-accelerated periodontitis progression." (PMID 40000642, 2025). "Interestingly, we found the downregulation of Synoviolin in periodontitis, which was correlated to the decreased ubiquitination of GSDMD, suggesting Synoviolin was responsible for GSDMD ubiquitination in periodontitis." (PMID 37506160, 2023). "All these results demonstrated that Synoviolin protected against periodontitis by regulating GSDMD." (PMID 37506160, 2023). "Since GSDMD and pyroptosis are involved in periodontitis, we hypothesized that Synoviolin might regulate GSDMD and pyroptosis in periodontitis by ubiquitinating GDDMD and promoting its degradation." (PMID 37506160, 2023). "In addition, the ubiquitination of GSDMD in PBMCs isolated from patients with severe periodontitis was further decreased." (PMID 37506160, 2023). "Therefore, we conclude that Synoviolin suppresses inflammasome activation and periodontitis by regulating GSDMD stability." (PMID 37506160, 2023).
periodontitis (continued). "Therefore, our data from in vitro and in vivo experiments elucidated that Synoviolin mediated the ubiquitination of GSDMD, which regulated the stability of GSDMD and the activation of inflammasome in periodontitis." (PMID 37506160, 2023). "The physiological roles of GSDMs other than GSDMD in periodontitis remain poorly understood." (PMID 36093182, 2022). "Through the construction of animal periodontitis models, we demonstrated that GSDMD-mediated PDLSC pyroptosis participated in periodontal tissue destruction and could be therapeutically targeted." (PMID 33869229, 2021). "The co-staining results demonstrated that GSDMD was enriched in PDLSCs in periodontitis patients." (PMID 33869229, 2021). "Additionally, strong immunostaining for GSDMD was observed in the periodontal ligaments from periodontitis patients." (PMID 33869229, 2021). "Moreover, Z-LEVD-FMK, a caspase-4 specific inhibitor, led to inhibition of GSDMD cleavage, caspase-4 activation, and IL-1β release in a periodontitis rat model." (PMID 35008798, 2021). "The induction of GSDMD in human periodontitis and ligature-induced rat periodontitis and the restorative effect of IL-1β antibody and caspase-4 inhibitor in rat periodontitis led us to hypothesize that GSDMD-driven pyroptosis was probably the key determinant of periodontitis." (PMID 33869229, 2021). "Moreover, we revealed that BMAL1/GSDMD signaling acts as a coordinator of shift work-related circadian disruption and periodontitis progression, providing a potential guidance for the development of intervention strategies targeting circadian clock against periodontitis." (PMID 40000642, 2025). "Although our study provides new insights into the mechanisms of circadian disruption-deteriorated periodontitis and the previously undiscovered roles of BMAL1 in GSDMD-mediated pyroptosis, some limitations should be noted." (PMID 40000642, 2025). "The essential genes PRKCB, GSDMD, ARMCX3, and CASP3 affected periodontitis and osteoporosis by involving the MAPK signaling pathway and the neutrophil extracellular trap formation." (PMID 38511766, 2024). "In line with this, also reported that hyperglycemia promotes GSDMD-dependent pyroptosis of macrophages through NLRC4 phosphorylation, thus activating NF-κB signaling in HGFs and further aggravating periodontitis." (PMID 36093182, 2022). "Increasing evidence indicated that E3s, such as CUL3, Nedd4‐2, Synoviolin, FBXL19, PDLIM2, TRIMs and TRAFs, modulate inflammatory responses and bone resorption in periodontitis through multiple classical signalling pathways, including NLRP3, GSDMD, NF‐κB, Wnt/β‐catenin and Nrf2." (PMID 39626954, 2025). "Unfortunately, in the present study, we did not distinguish the specific lysine linkage of GSDMD in periodontitis." (PMID 37506160, 2023). "Interestingly, the protein level of GSDMD and p31 in PBMC isolated from patients with severe periodontitis was higher than in PBMCs isolated from patients with mild periodontitis." (PMID 37506160, 2023). "Mechanistic investigation revealed that the caspase-4/GSDMD/IL-1β non-canonical pyroptosis pathway was the major contributor to the pathogenesis of periodontitis." (PMID 33869229, 2021). "Thus, the citrullination in neutrophils from patients with periodontitis might be a consequence of more intense NET formation, as PAD4 activation is a secondary process driven by GSDMD pores; H3 citrullination is time-dependent." (PMID 38542287, 2024). "Limited evidence in periodontitis revealed that P. gingivalis, Mycoplasma salivarium, Treponema denticola surface protein Td92, E. faecalis, and LPS can induce pyroptosis in macrophages through the NLRP3/caspase-1/GSDMD pathway, contributing to the pathogenesis and development of periodontitis." (PMID 36093182, 2022).
periodontitis (continued). "Furthermore, GSDMD, the key executor of pyroptosis, was found to be highly expressed and activated in periodontitis tissues, and we reported for the first time that PDLSCs (CD90+) were the source of IL-1β production in periodontitis patients." (PMID 33869229, 2021). "In this work, we also confirmed that the activation of caspase-4/11 was elevated in human periodontitis samples and in murine periodontitis models and that P. gingivalis (a gram-negative periodontopathogen) induced PDLSC pyroptosis with the cleavage of GSDMD and IL-1β release." (PMID 33869229, 2021).
diabetes (18 papers, 2021 to 2025). "The contributory role of GSDMD has been implicated in diabetes mellitus, liver diseases, cardiovascular diseases, neurodegenerative diseases, and inflammatory bowel disease (IBD)." (PMID 39253076, 2024). "GSDMD is involved in the pyroptosis-related inflammasome pathway to cause damage in pancreatic tissues during diabetes mellitus, where injured and dysfunctional pancreatic β cells are responsible for insulin deficiency and hence diabetes progression." (PMID 39253076, 2024). "Finally, the results suggested that high expression of GSDMD and diabetes increased the risk of MACE after AMI." (PMID 36544106, 2022). "Furthermore, univariate and multivariate Cox regression analyses suggested that the GSDMD level and diabetes were significantly related to the risk of MACE after AMI." (PMID 36544106, 2022). "Moreover, AGEs produced by high-glucose induced pyroptosis in human kidney-2 cells through AGEs/NLRP3/GSDMD were found to accelerate the kidney damage caused by diabetes." (PMID 36093182, 2022). "Given its pivotal role in diabetes-associated inflammation, the NLRP3 inflammasome and Gasdermin D have emerged as therapeutic targets." (PMID 40427455, 2025). "Pharmacological inhibition on NLRP3/caspase 1/GSDMD cascade by empagliflozin was shown to be beneficial against pancreatic damage during diabetes." (PMID 39253076, 2024). "Diabetes also inhibits the proliferation and differentiation of osteoblasts in alveolar bone by activating the caspase-1/GSDMD/IL-1β pathway." (PMID 36093182, 2022). "Pyroptosis is distinct from apoptosis, and is a form of gasdermin D (GSDMD)-dependent inflammatory programmed cell death that is involved in tubular injury in diabetes." (PMID 36186139, 2022). "In summary, our data suggested that empagliflozin protects the pancreatic tissues from diabetes mellitus-induced injury by downregulating the NLRP3/caspase-1/GSDMD pyroptosis-related inflammasome pathway." (PMID 34823419, 2021). "Diabetes, a sterile inflammatory condition, is related to increased pyroptosis, characterized by increased caspase-1, IL-1β, and GSDMD in skeletal muscle." (PMID 34360821, 2021). "Many studies investigated the mechanism mediating the renoprotective effect of GSDMD regulation in the kidneys of patients and animal models with diabetes." (PMID 34867412, 2021). "The NLRP3/GSDMD axis was shown to modulate pyroptosis and inflammation in pancreatic β cells during hyperglycemia, implying the role of GSDMD in promoting the progression of diabetes mellitus." (PMID 39253076, 2024). "Accordingly, we hypothesized that NLRP3 dysregulation might affect pyroptosis in diabetic ED and evaluated pyroptosis markers (GSDMD, GSDMD-N, pro-caspase-1, cleaved-caspase-1, ASC, IL-1β, and IL-18)." (PMID 39014129, 2024). "In this observation, quantitative analysis of fluorescence intensity showed that compared with the diabetes group, the average optical density of GSDMD in the SCU treatment group tended to decrease, supporting caspase-1 regulating GSDMD pathway has been involved in our observation." (PMID 37081038, 2023). "Immunohistochemical fluorescence assay revealed that the levels of NLRP3, ASC, and GSDMD were significantly increased in the ApoE−/− mice following induction of diabetes and consistent feeding with a Western diet compared with the ApoE−/− mice fed with a control diet." (PMID 36425580, 2022). "Therefore, 12 weeks of Tai Chi intervention can significantly decrease the expressions of NEK7, NLRP3, ASC, Caspase-1, GSDMD, IL-1β, and IL-18, while increasing the expression of irisin in pre-diabetes." (PMID 36248820, 2022). "This study evaluated whether empagliflozin (EMPA) protects the pancreas from diabetes mellitus-induced injury by downregulating the nucleotide-binding oligomerization domain-like receptor protein 3 (NLRP3)/caspase-1/Gasdermin D (GSDMD) pyroptosis-related inflammasome pathway in vitro and in vivo." (PMID 34823419, 2021).
diabetes (continued). "Our in vitro study confirmed that empagliflozin reduced the activation of NLRP3 and the expression of pyroptosis-related inflammasomes in pancreatic β cells under a high glucose environment, suggesting that the NLRP3/caspase-1/GSDMD pathway may be a potential therapeutic target for diabetes." (PMID 34823419, 2021). "At the same time, considering some other variables in AMI such as diabetes, CRP and hypertension, we analyzed the correlation between GSDMD expression level and them." (PMID 36544106, 2022). "Metformin has also been reported to alleviate diabetes-induced macrophage dysfunction by negatively regulating cytoplasmic dsDNA/AIM2, which could activate caspase-1 and cleave GSDMD-mediated pyroptosis." (PMID 38067543, 2023). "However, very recently, we could demonstrate that hematopoietic deficiency of a key protein involved in pyroptosis, Gasdermin D, did not alter necrotic core expansions in response to diabetes, arguing that other pathways are involved in driving necrotic core expansion in diabetes." (PMID 37378396, 2023).